JAK2 (Janus kinase 2)
Diseases named in the same sentence as JAK2 in open-access papers (continued):
Sharing a sentence is not in itself a finding about the gene and the disease.
colorectal cancer (continued). "Phosphorylated molecules p-JAK2 and p-STAT3 are significantly increased in colorectal cancer cells overexpressing COX2 (cyclooxygenase-2)." (PMID 33198257, 2020). "Berberine markedly decreased the levels of phosphorylated JAK2 and phosphorylated STAT3 in colorectal cancer cells and effectively interrupted the COX2/JAK/STAT signaling pathway, which was observed as a decrease in the level of metalloproteinases." (PMID 33198257, 2020). "A previous study demonstrated that, in colorectal cancer, phosphorylation levels of STAT3 and JAK2 were inhibited by RPN2 siRNA 28, indicating that the JAK/STAT pathway was positively correlated with RPN2 expression." (PMID 31743606, 2020). "Berberine significantly decreased the phosphorylated levels of JAK2 and STAT3 in colorectal cancer cells." (PMID 30987378, 2019). "Recently, reports have found that inhibition of the JAK2/STAT3 pathway induces cell cycle arrest and apoptosis in colorectal cancer (CRC) cells." (PMID 30564118, 2018). "We also illustrated that the JAK2 and STAT3 activation play a significant role in the promotion of metastasis in colorectal cancer." (PMID 29348540, 2018). "Of note, ursolic acid attenuated the expression of anti-apoptotic proteins such as Janus kinase 2 (JAK2) and signal transducer and activator of transcription 3 (STAT3) and also blocked nuclear translocation of STAT3 in colorectal cancer cells." (PMID 30597956, 2018). "Western blotting analysis revealed that CC-MSC-CM resulted in increased phosphorylation of JAK2, STAT3, and AKT in colorectal cancer cells; all three were activated by stimulation with IL-6." (PMID 29348540, 2018). "B7-H4 siRNA can effectively inhibit proliferation, invasion, and migration of LOVO cells by targeting CXCL12/CXCR4 and JAK2/STAT3 signaling, which can serve as a new target for colorectal carcinoma treatment." (PMID 26078947, 2015). "Similarly, in the colorectal cancer microenvironment, ANGPTL4 overexpression in endothelial cells activated JAK2/STAT3 signaling, enhancing angiogenesis and metastasis." (PMID 40616161, 2025). "In this study, we have demonstrated that exosomal miR-320d derived from colorectal cancer cells enhances angiogenesis in vascular endothelial cells and promotes cancer cell metastasis by downregulating GNAI1 expression, enhancing JAK2/STAT3 protein phosphorylation, and increasing VEGFA expression." (PMID 39695099, 2024). "Additionally, Dp has also been shown to regulate the JAK2/STAT3 signaling pathway, inducing apoptosis in colorectal cancer cells." (PMID 39781272, 2024). "Signal transducer and activator of transcription 3 (STAT3) is a critical transcription activator in angiogenesis; it has been reported that the JAK2/STAT3 and mTOR/STAT3 signaling pathways promote apoptosis and inhibit proliferation and angiogenesis in colorectal cancer cells." (PMID 38257275, 2024). "The role of FOXQ1 in immunology has been preliminarily confirmed, with previous research showing that cancer-related macrophages induce epithelial–mesenchymal transition by regulating the JAK2/STAT3/miR-506-3p/FOXQ1 axis, thereby enhancing the invasion and migration of colorectal cancer cells." (PMID 36118871, 2022). "Interacting with JAK2 and phosphorylating it to promote the JAK2/STAT3 pathway is one way that PTK6, and particularly phosphorylated PTK6, might enhance the stemness of colorectal cancer cells." (PMID 36405012, 2022). "Reportedly, IL-6 secreted by colorectal cancer-derived MSCs could activate JAK2/STAT3 signaling and promote the progression of colorectal cancer." (PMID 34789315, 2021). "Interestingly, p-JAK2 and p-STAT3 were found to be remarkably enhanced in COX2 (cyclooxygenase-2) overexpressing colorectal cancer cells." (PMID 30987378, 2019). "JAK2 and STAT3 activation have an important effect on metastasis in colorectal cancer." (PMID 29348540, 2018).
colorectal cancer (continued). "In conclusion, microRNA-375 might function as a tumor-repressive gene to inhibit cell proliferation, mainly through targeting both JAK2/STAT3 and MAP3K8/ERK signaling pathways in colorectal cancer." (PMID 28186962, 2017). "Furthermore, another study found that during RT, the JAK2/STAT3 signaling pathway was activated, which in turn activated downstream CCND2 expression and enhanced CSCs properties, leading to radioresistance in colorectal cancer." (PMID 38355684, 2024). "Furthermore, related researches have proved that upregulated ROS could abrogate JAK2/STAT3 signaling to suppress tumor growth in cancers such as hepatocellular carcinoma, multiple myeloma, and colorectal cancer." (PMID 32576206, 2020). "Conversely, Actinomyces-induced interleukin-6 (IL-6) secretion may activate the JAK2/STAT3 pathway, increasing hepcidin production and systemic iron sequestration, a mechanism analogous to gut microbiota-mediated inflammatory pathways observed in colorectal cancer progression." (PMID 40149653, 2025).
anemia (114 papers, 2006 to 2026). A reduction in the number of red blood cells, the amount of hemoglobin, and/or the volume of packed red blood cells. "Anemia and leukopenia, which are characteristics of the myelodepletive phenotype, were associated with a low JAK2 V617F allele burden (<25%) and inferior survival." (PMID 37444441, 2023). "The myelodepletive phenotype is associated with progressive anemia and/or thrombocytopenia, modest splenomegaly, more high molecular risk mutations, lower mutant JAK2 allele burden, and inferior outcomes." (PMID 37444441, 2023). "The strong association of mutant U2AF1 with anemia and thrombocytopenia was sustained when mutated-JAK2 and wild type JAK2 patients were analyzed independently; U2AF1 mutations directly associated with JAK2V617F." (PMID 36434065, 2023). "Therapy with ruxolitinib, a potent JAK1/JAK2 inhibitor approved for the treatment of MF-related splenomegaly or symptoms, can be associated with dose-dependent anemia, mostly emerging in the first 12 weeks of treatment." (PMID 34017073, 2021). "Because ruxolitinib lacks strict specificity for JAK2 and has drug side effects causing anemia and thrombocytopenia, exploring new JAK2 inhibitors for the treatment of hematologic malignancies is urgent and important." (PMID 34588425, 2021). "Limitations in targeting JAK2 are caused by the dependency of normal hematopoiesis on JAK2, resulting in on-target toxicity in the form of anemia and thrombocytopenia in patients with MF treated with JAK2 inhibitors." (PMID 32983162, 2020). "Given its mechanism of action as a JAK1 and JAK2 inhibitor, the most common AEs associated with ruxolitinib were anemia and thrombocytopenia." (PMID 29804268, 2018). "The embryonically lethal anemia observed in both JAK2- and STAT5-deficient mice, which resemble Epo- or EpoR-deficient mice, demonstrates the crucial roles of JAK2 and STAT5 in Epo-dependent erythropoiesis." (PMID 25790231, 2015). "Because thrombopoietin and erythropoietin signal through JAK2, inhibition of JAK2 with ruxolitinib treatment is associated with dose-dependent thrombocytopenia and anemia." (PMID 24283870, 2013). "For instance, improper inhibition of JAK2 might cause thrombocytopenia and anemia; improper inhibition of JAK3 might cause immunodeficiency and infection." (PMID 40746612, 2025). "JAK inhibitors with selective targeting, such as upadacitinib may offer a more favourable risk-benefit profile due to the reduced risk of JAK2-related side effects, such as anaemia and thrombosis." (PMID 41327887, 2025). "However, in transplant-age patients with the CALR mutation, symptoms response was significantly lower (52.5% versus 69.3% in JAK2-mutated patients, p = 0.01) and overall anemia rate was higher (55.4% versus 42.9%, p = 0.05)." (PMID 39831987, 2025). "It is recent FDA-approval may reveal whether more selective JAK2 inhibition improves therapy-associated thrombocytopenia and anemia." (PMID 35903543, 2022). "Notably, the cumulative incidence of anemia was lower in PMF patients harboring the driver CALR mutation versus JAK2- and MPL- mutants; conversely, “triple negative” patients for the three driver mutations manifested the highest cumulative incidence of anemia." (PMID 35045875, 2022). "There are still limitations in targeting JAK2 that are mainly caused by the dependency of normal hematopoiesis on JAK2, resulting in a specific toxicity expressed as the combination of anemia and thrombocytopenia in patients with MF treated with JAK2 inhibitors." (PMID 35887218, 2022). "The thrombocytopenia and anemia associated with fedratinib may be related to its on-target inhibition of WT JAK2 and off-target inhibition of FMS-like tyrosine kinase 3 (FLT3) and bromodomain-containing protein 4 (BRD4)." (PMID 35903543, 2022). "Anemia was positively correlated with the JAK2 and DNMT3A mutations." (PMID 36139644, 2022).
anemia (continued). "Other side effects of JAKi include cytopenias, anemias, and thrombocytopenia, as well as the potential for malignancy.This risk is thought to be due to JAK2 specific inhibition, as the cytokine receptors for erythropoietin and thrombopoietin signal through JAK2." (PMID 34122106, 2021). "However, all of these studies were focused on the inhibition of JAK2; JAK2 specifically mediates cytokine signaling for red blood cells and platelets, and its inhibition causes anemia and low platelets." (PMID 27278657, 2016). "Compared to ruxolitinib, JTE-052 might be expected to have a lower risk of anemia in the clinical setting owing to its relatively weak inhibition of JAK2/Tyk2 signaling pathway." (PMID 25387665, 2015). "Also, while generally well tolerated, JAK2 inhibitors caused some degree of unwanted myelosuppression, particularly anemia and thrombocytopenia." (PMID 23382981, 2013). "The difference in isoform specificity among JAK inhibitors might account for the tolerability and efficacy of each agent with an increased risk for anemia and other hematologic adverse events resulting from substantial JAK2 inhibition of tofacitinib compared to newer-generation agents." (PMID 40430558, 2025). "Treatment-emergent anemia (CALR: 35.7% versus JAK2: 30.4%, p = 0.37), overall and treatment-emergent thrombocytopenia were comparable in the two groups (p = 0.49 and p = 0.60, respectively)." (PMID 39831987, 2025). "Higher exposures erode specificity, and JAK2 inhibition by pan-JAK inhibitors frequently results in dose-dependent anaemia, highlighting the link between JAK2 signalling and erythropoiesis." (PMID 41327887, 2025). "Inhibition of JAK2 can impact hematopoiesis, leading to anemia or thrombocytopenia, necessitating regular blood monitoring in clinical settings." (PMID 41497807, 2025). "While JAK2 inhibition can potentiate anti-inflammatory effects, potential off-target risks (e.g., anemia, thrombocytopenia) warrant caution." (PMID 40430558, 2025). "Anemia and thrombocytopenia were the most common side effects related to the myelosuppression mediated by JAK2 inhibition." (PMID 40973846, 2025). "We have used JAK-2 inhibitor therapy only in patients with persistent disease-related symptoms (ruxolitinib) or anaemia (momelotinib)." (PMID 41464542, 2025). "Here we present a 69-year-old female patient with anemia and splenomegaly, exhibiting CALR exon 9 mutation (c.1099_1150del52) and JAK2 V617F negativity." (PMID 40761243, 2025). "Anemia and thrombocytopenia were the most common side effects, related to myelosuppression mediated by JAK2 inhibition." (PMID 40973846, 2025). "The MPL mutation is present in 4–5% of JAK2-negative patients, whereas IMF is a complex condition characterized by JAK2 V617F mutation and CALR-gene mutation, in which myeloproliferation often coexists with anemia or thrombocytopenia." (PMID 38672756, 2024). "Anemia and interstitial pneumonia both significantly improved following treatment with a Janus kinase 2 gene inhibitor." (PMID 39659792, 2024). "This post hoc descriptive analysis of the phase 3 SIMPLIFY-2 trial evaluated the relative benefits of this approach versus switching to the JAK1/JAK2/activin A receptor type 1 inhibitor momelotinib in patients for whom anemia management is a key consideration." (PMID 38990433, 2024). "JAK2 inhibition, an effective strategy for treating malignancy, results in anemia and thrombocytopenia." (PMID 39403378, 2024). "Given that JAK2 is essential for the formation of red blood cells and platelets, administration of JAK2 inhibitors induces anemia and low platelet counts." (PMID 36507538, 2022). "Of the 15 subjects enrolled into the first stage, seven (46.7%) required dose reductions for ruxolitinib, primarily due to anemia, a known on-target (JAK2) toxicity, including 3 (20%) that required two dose reductions (20 mg followed by 15 mg)." (PMID 36369506, 2022).
anemia (continued). "The anemia will lead to increased erythropoietin levels to compensate for the tissue hypoxia, which consequently stimulates the Janus kinase 2 (JAK2)-dependent phosphorylation cascade." (PMID 36295656, 2022). "Momelotinib, an inhibitor of ACVR1/ALK2, JAK1 and JAK2, demonstrated activity against anemia, symptoms, and splenomegaly in the phase 3 SIMPLIFY trials." (PMID 35869266, 2022). "In terms of AEs, most of the next-generation Jak2 inhibitors are relatively well tolerated with the AEs, mainly including GI effects, fatigue, opportunistic infections and anemia." (PMID 34680353, 2021). "Momelotinib is a JAK1/JAK2 inhibitor, which in murine models of anemia in chronic disease, was shown to inhibit bone morphogenic protein receptor kinase activin A receptor type I (ACVR1)–mediated hepcidin expression, which stimulated erythropoiesis." (PMID 32198525, 2020). "That is why side effects including anemia, neutropenia and thrombopenia were observed during inhibition of JAK2 within treatment with pan-inhibitors of the JAKs enzyme family." (PMID 32796683, 2020). "First clinical reports suggested a benefit of oral JAK1/2 inhibitors on CLE skin lesions, but the systemic use of these drugs is limited by side effects, e.g., anemia and thrombopenia, which mainly depend on JAK2 blockade." (PMID 32194562, 2020). "There is also much interest in the development of mutant-specific inhibitors of JAK2 that should, in theory, spare wild type JAK2 and avoid on-target toxicities such as anemia and thrombocytopenia, among others." (PMID 32903304, 2020). "One crucial disadvantage of these drugs are their side effects, including anemia and thrombopenia, mainly depending on JAK2- and JAK3 inhibition, which prompted us to focus on JAK1 in this preclinical project." (PMID 32194562, 2020). "Androgens, prednisone, danazol, thalidomide, and lenalidomide have been used to treat MF-related anemia, and hydroxyurea, JAK2 inhibitors, and other agents have been used to treat splenomegaly." (PMID 32198525, 2020). "Most JAKi are likely to induce cytopenias, decreased neutrophil counts and anemia because of their more or less specific inhibition of JAK2 and erythropoietin together with other hematopoietic growth factors as IL-6 and IL-11 signaling." (PMID 32796683, 2020). "Although Hb levels decreased in a similar manner, the incidence of anemia was significantly higher in the CALR‐ET group than in the JAK2‐ET group, because baseline Hb levels were significantly lower in the CALR‐ET group." (PMID 31107982, 2019). "• JAK2 inhibitors, in particular ruxolitinib, are used to treat PMF and produce significant reduction in splenomegaly, but are associated with significant anemia and thrombocytopenia." (PMID 31244289, 2019). "Regarding treatment‐related adverse events, the number of adverse events (anemia) was significantly higher in the CALR‐ET group (five patients [45.5%]) compared with the number of such events in the JAK2‐ET group (five patients [14.7%]; P = 0.037)." (PMID 31107982, 2019). "The increase in erythropoietin driven by anemia and the consequent cascade of Janus Kinase 2 (JAK2)-dependent phosphorylation events ultimately expand the erythroid lineage within the bone marrow." (PMID 29316681, 2018). "It is essential for JAK2 inhibitors to not only show potent enzymatic inhibition, but selectivity toward JAK2 to prevent off target side effects, such as peripheral neuropathy, anemia, and thrombocytopenia." (PMID 30564118, 2018). "JAK2 is responsible for the activation of molecules involved in RBC production, and thus the increase in JAK2 gene expression in the cured younger brother is probably involved in the disappearance of his anemia symptoms." (PMID 28185911, 2017). "As such, it inhibits the catalytic activity of wild-type JAK2 as well as mutant JAK2, which can lead to side effects such as anemia and thrombocytopenia." (PMID 29379470, 2017).